CCL18 (C-C motif chemokine ligand 18)
Diseases named in the same sentence as CCL18 in open-access papers (continued):
Sharing a sentence is not in itself a finding about the gene and the disease.
tumor (continued). "CCL18 serves as a marker of the M2 macrophage phenotype, which is associated with suppressive TME and tumor immune evasion." (PMID 38365809, 2024). "CCL18+ TAMs are immunosuppressive and participate in tumor proliferation, angiogenesis, and lymphangiogenesis." (PMID 39457004, 2024). "The high expression of CCL18 at the invasive front of human colorectal tumors correlates with advanced tumor staging, underscoring its clinical significance." (PMID 38221607, 2024). "Thirdly, TAMs are capable of secreting cytokines such as TGF-β, prostaglandin E2 (PGE2) and CCL18, which mediate tumor-promoting activity and immunosuppression in the TME." (PMID 38970071, 2024). "Flow cytometry analysis of fresh tumour samples verified that CCL18 was specifically expressed in CD68+ macrophages in the CRC microenvironment." (PMID 37935468, 2024). "All of these results suggested that tumour-infiltrating CCR8+ Tregs were retained in the TME by CCL18+ macrophages." (PMID 37935468, 2024). "We finally confirmed CCL18-PITPNM3 signaling network showed strongest interaction occurred between epithelial/tumor cells and macrophages based on cell interaction network inferred from ESCC scRNA-seq data." (PMID 36850011, 2023). "Other mechanisms include decreased VEGF, MMP, and CCL18 secretion relative to pro-tumor M2 macrophages, which prevents angiogenesis and metastasis." (PMID 38035101, 2023). "The gray intensity analysis showed that three cytokines, IL-6, IL-8, and CCL18, were abundant in the chemoresistant tumor samples with plentiful CD10+GPR77+ CAFs, which were validated by ELISA." (PMID 36418470, 2023). "Overall, high levels of CCL1 and CCL18 in OC tissues can recruit CD4+CCR8+ Tregs into tumor tissues by recognizing CCR8 on cells and remodeling their inhibitory phenotypes, making them have stronger immunosuppressive phenotypes and proliferative abilities." (PMID 37950246, 2023). "Studies using a xenograft model showed that CCL18 increased tumor size and induced lung metastasis, suggesting that TAMs can promote OS growth and distant metastasis by secreting CCL18." (PMID 37206921, 2023). "CCL18 levels in ascites and the serum of OC patients are elevated, which increases tumor migration and metastasis." (PMID 37298230, 2023). "Proinflammatory CD80, anti‐inflammatory CD206, CCL18, and CCL22, and the tumor‐associated markers including MMPs, MGLL, and TLR4 were expressed by a low proportion of monocytes (<1%), but significantly upregulated in TAM." (PMID 38037545, 2023). "CCL18+ macrophages can be found in solid tumor tissues and in an immunosuppressive state in tumor tissues." (PMID 38347955, 2023). "Cytokines and chemokines derived from TAM2, such as IL1/8 and CCL18, can enhance the epithelial–mesenchymal transition in tumor tissues through various signaling pathways, which leads to advanced tumor invasion and metastasis." (PMID 37628967, 2023). "We then added neutralizing antibodies against CCL18, IL-6 and IL-8 to NBFs treated with fresh chemoresistant tumor CM." (PMID 36418470, 2023). "According to our previous study, CCL18 was not only highly expressed in tumor tissues and the serum of NSCLC patients but also significantly associated with a poor prognosis." (PMID 36217054, 2023). "Studies have shown that hypoxia upregulates the TAMs-derived cytokines such as vascular endothelial growth factor (VEGF), TGF-β, CCL18 and IL-6, which were involved in tumor progression and metastasis." (PMID 37884960, 2023). "TAMs, abundant components in the TME, release several cytokines and chemokines like IL‐6, CCL18, and IL‐8 for interacting with their respective receptors on cancer cells, thus activating oncogenic pathways and inducing tumor malignancy." (PMID 37846367, 2023). "The effects of CCL18+ TAM subpopulation on tumor cells include tumor cell proliferation, migration induction, invasion, EMT, angiogenesis, and lymphangiogenesis." (PMID 38347955, 2023).
tumor (continued). "In conclusion, M2 macrophages secrete CCL18 to promote tumor invasion and metastasis, tumor angiogenesis and immunosuppressive function, so as to promote tumor progression." (PMID 36173487, 2023). "CCL18-PITPNM3 signaling network inferred from scRNA-seq dataset showed the strongest interaction occurred between epithelial/tumor cells and macrophages." (PMID 36850011, 2023). "CCL18 is primarily generated and released into the TME by tumor-associated macrophages (TAMs), where it promotes invasion and metastasis." (PMID 36830578, 2023). "Among the top upregulated chemokines, CCL18 was highly expressed in tumor and correlated with poor prognosis." (PMID 36850011, 2023). "CCL18 also had an influence on the proliferation of cancer cells, but this effect was dependent on the type of tumor." (PMID 38347955, 2023). "Recent studies have demonstrated that high expression of CCL18 in CRC patients is correlated with advanced tumour staging and liver metastasis, which is similar to our findings in lung metastasis of CRC." (PMID 37024866, 2023). "The effects of CCL18 on tumor cells were similar to SPP1 TAM, implying that this CCL8+ macrophage subpopulation was originated from SPP1+ TAMs." (PMID 38347955, 2023). "In TMEM, TAMs can produce EGF (epidermal growth factor) and secrete chemokine CCL18, and tumor cells can also secrete chemokine CCL18 and produce cytokine CSF-1, all of which play important roles in the process of tumor cell invasion." (PMID 36131942, 2022). "The results of the present study suggest that NSCLC cells release microvesicles that activate MCs to release several chemokines, among them CCL18, which thereafter serves as an angiogenic factor due to its ability to promote tumor angiogenesis." (PMID 35159163, 2022). "CCL18 is abundantly released by TAMs, and its expression in TME is associated with tumor metastasis and decreased patient survival." (PMID 34914196, 2022). "CCL18 expression in the enhancing tumor region and the tumor core was more than seven times higher than in the peritumoral area." (PMID 35955670, 2022). "Macrophage-derived cathepsins, SPARC, or CCL18 improve tumor cell adhesion to extracellular matrix proteins and promote tumor cell migration." (PMID 36613819, 2022). "Tumor-associated macrophages (TAMs) have been reported to be associated consisting of highly expressed CCL2, CCL3, CCL5, CCL18, CXCL1, and CXCL12 in the TME." (PMID 35935996, 2022). "CCL18 plays an important role in tumorigenesis in GBM, as shown by the survival data of patients with this cancer which is inversely correlated with CCL18 levels in the tumor." (PMID 35955670, 2022). "The tumor-promoting cytokine CCL18 was also found to be intimately involved in the induction of the M2 phenotype in macrophages." (PMID 36138435, 2022). "GBM releases extracellular vesicles containing CCL18 to allow surrounding tumor cells to acquire resistance to temozolomide." (PMID 36177003, 2022). "Although its underlying mechanisms are still unclear, future anti-tumor treatment should be informed by the contradictory role of CCL18 in tumor progression in order to obtain good therapeutic efficacy." (PMID 35327584, 2022). "The C-C motif chemokine ligands, CCL17, CCL18, and CCL22, which are secreted from activated TAMs, are associated with the enlargement of tumor size and the promotion of tumor metastasis, and the recruitment of Treg cells." (PMID 35955737, 2022). "CCL18 enhances the recruitment of Tregs into the tumor; in contrast, blocking CCL18 inhibits Tregs migration and suppresses tumor growth." (PMID 35183252, 2022). "Depending on the CCL18 secretion in tumor-decellularized matrices, macrophages differentiate toward an anti-inflammatory phenotype and then facilitate CRC cell invasion." (PMID 35935996, 2022). "MCs were found to accumulate in the tumor stroma of different human cancer types in which CCL18 was highly expressed, such as lung, breast, ovarian and others." (PMID 35159163, 2022).
tumor (continued). "Among the various cells constituting TME, for example, tumor-associated macrophages (TAM) are increased in MF and SS lesions with the increased expression of CCL18 and CCL22, which promote a Th2-biased microenvironment." (PMID 34884736, 2021). "The CCL8 gene is only detected on monocytes/TAM and the DC cluster, whereas the CCL18 gene is expressed more widely on immune clusters (neutrophils, B cells, plasma cells and T cells) but, also, specifically, on tumor cell clusters from the lung tissue." (PMID 33924428, 2021). "Of these, CD163high TAM are of particular relevance, as they express metastasis‐promoting genes, such as CCL18, CCL23, KITLG and VEGFB17 and are associated with rapid tumour progression and early relapse in HGSC patients." (PMID 34841720, 2021). "To further study potential pathways for chemotherapy-sensitive tumor cells to benefit from immunotherapy and the molecular mechanisms of CCL18 and BCL2A1, we performed GSEA among 186 KEGG pathways, including the Toll-like receptor signaling pathway." (PMID 35265629, 2021). "Pulmonary and activation-regulated chemokine (PARC)/CCL18 exerts rather pro-tumoral functions in tumor progression." (PMID 34503058, 2021). "The most secreted CCL18+ M2 macrophage phenotype is negatively related to survival, large tumor size and TNM stage and at the same time with stimulation of invasion and tumor dissemination and neoangiogenesis." (PMID 34503196, 2021). "CCK-8, transwell, and FCM assay were used to study the effect of CCL18 on tumor progression in vitro." (PMID 34354751, 2021). "In summary, by using a comprehensive bioinformatics analysis, we identified three tumor microenvironment-related genes (ADGRE1, CCL18, and LILRA6) which were closely associated with the prognosis of PCPG." (PMID 33795528, 2021). "According to the RT-qPCR assay, tumor tissues assumed the overexpression of CCL18 compared with normal tissues." (PMID 34354751, 2021). "The CCL18 is a target gene of miR-128, and by regulating the expression of CCL18, miR-128 can regulate tumor invasion and metastasis." (PMID 35059433, 2021). "This is related to the interaction of IL-32θ with protein kinase C-δ (PKCδ), although the importance of PKCδ in the effects of CCL18 on the tumor cell still needs to be thoroughly investigated." (PMID 33114763, 2020). "The level of CCL18 is proportional to the level of disease development: stage, Ki67 expression level in the tumor and lymph node metastasis." (PMID 33114763, 2020). "For example, it has been found that the high expression of CCL18 in tumor cells promotes invasion and migration of ovarian cancer cells by activating their own mTOR signaling." (PMID 33224886, 2020). "M2 macrophages can secrete tumor-promoting factors, including Arg-1, TGF-b, and CCL18, which are proficient in tumor initiation and progression." (PMID 33052231, 2020). "These cells secrete many chemokines into the tumor microenvironment, including especially a large amount of CCL18." (PMID 33114763, 2020). "Cytokines like TGF-β and CCL18 secreted by TAMs can induce invasive phenotype and mesenchymal markers in tumor cells." (PMID 32992449, 2020). "Among the various factors in the M2 condition medium, we identified CCL18 as one of the tumor-promoting cytokines involved in FAK-PI3K-AKT activation." (PMID 33052231, 2020). "Then, we cultured parental tumor cells with different concentrations of CCL18 recombinant protein and found that the FAK-PI3K-AKT pathway was activated." (PMID 33052231, 2020). "Studies in xenograft models indicated that CCL18 increased the tumor size and induced lung metastasis, indicating that TAMs, by secreting CCL18 promote metastasis and tumor growth in OS." (PMID 32717819, 2020). "Other functions of CCL18 in the tumor include participation in the intercellular communication dependent on extracellular vesicles." (PMID 33076281, 2020).
tumor (continued). "CCL18 is produced in large amounts in every tumor, where it participates in the recruitment of Treg cells and affects the phenotype of TAMs." (PMID 33114763, 2020). "CCL18 also increases the proliferation of cancer cells, but this effect depends on the type of tumor." (PMID 33076281, 2020). "Many chemokines involved in this process, not only CCL18, are also produced by TAMs in the neoplastic tumor." (PMID 33114763, 2020). "In our study, we addressed that the knockdown of CCL18 partially interrupted laparotomy‐induced tumor growth, whereas knockdown of CCL18 also suppressed laparotomy‐induced angiogenesis." (PMID 30216450, 2019). "C‐C motif chemokine ligand 18 (CCL18) expression was significantly upregulated after laparotomy in tumor tissue and the peritoneal cavity of tumor‐bearing mice, and it was positively correlated with the recruitment of Tregs." (PMID 30216450, 2019). "Through analysis of Tregs, we found an upregulated proportion of Tregs in tumor tissue, peritoneal cavity, and peripheral blood after laparotomy, but this enhancement was blocked after CCL18 knockdown." (PMID 30216450, 2019). "In previous studies, CCL18 was demonstrated as a potential regulator in tumor progression and metastasis in which enhanced CCL18 expression level was found in various tumor tissues in presence of several malignancies." (PMID 30216450, 2019). "Foxp3 mRNA level was significantly increased in tumor tissues after laparotomy, whereas knockdown of CCL18 partially destroyed laparotomy‐induced upregulation of Foxp3." (PMID 30216450, 2019). "In our study, we demonstrated that upregulated CCL18 promoted the recruitment of Tregs into tumor tissues." (PMID 30216450, 2019). "Increased CCL18 production has been found in various tumor tissues in the presence of several malignancies." (PMID 30216450, 2019). "Functionally, CCL18 knockdown significantly reduces tumor growth and angiogenesis compared with control." (PMID 30216450, 2019). "In conclusion, we demonstrate that laparotomy promotes tumor progression with upregulation of CCL18 observed in laparotomy‐induced tumor tissue." (PMID 30216450, 2019). "As expected, abdominal surgery resulted in a significantly higher tumor volumes compared with control, whereas knockdown of CCL18 partially destroyed laparotomy‐induced tumor growth." (PMID 30216450, 2019). "While VEGF has clearly defined roles for enhancing tumor cell migration via stimulation of angiogenesis, CCL-18 is a key factor in the chemotaxis of naïve T-cells and immune-suppression in the TME." (PMID 31214501, 2019). "Meanwhile, ELISA assay confirmed that CCL18 protein level in the peritoneal cavity was increased, along with the relationship between the Foxp3 level and the CCL18 level in tumor tissues was shown." (PMID 30216450, 2019). "This study was conducted to analyze the possible role of CCL18 in promoting tumor progression after laparotomy, where Tregs was recruited in the presence of CCL18." (PMID 30216450, 2019). "The presence of CCL18 contributes to the subsequent recruitment of Tregs which shows relatively increased population in tumor tissues and peripheral blood after laparotomy." (PMID 30216450, 2019). "Inhibiting naive T cell recruitment into tumors by interfering with the CCL18-PITPNM3 interaction is a previously unappreciated potential strategy for tumor immunotherapy." (PMID 28290464, 2017). "Naive CD4+ T cells adhere to tumor slices in proportion to the abundance of CCL18-producing macrophages." (PMID 28290464, 2017). "In human xenograft models, CCL18 is also required for tumor cell invasion and metastasis, playing a role in integrin clustering." (PMID 28241846, 2017). "The effect of did not change when adjusting for tumors that did not progress within the first 6 months (n = 39) in order to exclude any possible interference of CCL18 production due tumor progression." (PMID 28957436, 2017).
tumor (continued). "As CCL18 serum levels correlate with tumor size we expect that CCL18 levels decrease after response to radiotherapy." (PMID 28957436, 2017). "In contrast, exposure to IL-4 and/or IL13 (24h) polarizes them towards pro-tumor M2-macrophage fate (aka tumor associated macrophages or TAMs), as detected by increased expression of the M2-macrophage biomarkers; CCL17 and CCL18 in them (see RT/PCR analysis)." (PMID 29262555, 2017). "Together, these results suggest that Tregs are generated from naive CD4+ T cells responding via PITPNM3 to CCL18 produced in the tumor." (PMID 28290464, 2017). "Clinicopathological analyses demonstrated that CCL18 expression is positively correlated with advanced tumor stage in OSCC patients." (PMID 26919103, 2016). "Tumor growth was increased in the CCL18 group compared with the control group, as evidenced by the increased weight and volume of HSC-6 subcutaneous xenografts." (PMID 26919103, 2016). "In situ hybridization (ISH) for miR98 in the tumor xenografts demonstrated that miR98 expression was significantly lower in the CCL18-treated animals carrying uninfected tumors or tumors infected with lentivirus carrying NC mimics than in the PBS-treated ones." (PMID 26244871, 2015). "When the xenografts reached a diameter of 5 mm, we performed intra-tumoral injection of CCL18 at a dosage of 0.1 μg/kg biweekly for 25 d and evaluated tumor metastasis to the lungs and livers 50 days after inoculation." (PMID 26244871, 2015). "In order to evaluate the influence of CCL18 on tumor vascularization, we detected the expression levels of the vascular endothelial marker CD31 in RM-1 homografts of mice model by immunohistochemistry analysis." (PMID 25197632, 2014). "CCL18 is relevant for activation of T-cells through MHC class II, and is a marker for tumor-associated macrophages." (PMID 24495478, 2014). "Whilst the classical 7-TM receptor for CCL18 remains to be identified, PITPNM3 has been reported to mediate the CCL18 induced recruitment of tumor cells." (PMID 23951310, 2013). "As high levels of Arg II are consistently detected in tumor infiltrated M2 macrophages that express CCL18, we also analyzed the expression levels of CCL18 in these tumor samples, and their correlation with Arg II and mSHMT protein expression." (PMID 24223914, 2013). "The data presented here demonstrate that CCL18 is able to trigger events involved in tumor metastasis such as change from primary epithelial tumor cells into migratory mesenchymal cells, chemotaxis, and invasion." (PMID 23349697, 2013). "The correlation between serum CCL18 and tumor stage implies that CCL18 is a surrogate marker for tumour size." (PMID 22848587, 2012). "A range of cytokines and their receptors are known to be aberrantly expressed in tumor cells and so it is conceivable that CCL18 can act in a paracrine fashion during tumor initiation/establishment." (PMID 22629457, 2012). "To verify that serum CCL18 concentrations correlate with tumor size we estimated tumor volumes by the pathological data and correlated the tumor volume with serum CCL18 concentrations." (PMID 22848587, 2012). "Examination of tumor tissue located the origin of CCL18 in a subpopulation of TAMs based at the tumor front." (PMID 22848587, 2012). "HBD-3 stimulated the expression of tumor-promoting cytokines, including interleukin-1α (IL-1α), IL-6, IL-8, CCL18, and tumor necrosis factor-α (TNF-α) in macrophages derived from human peripheral blood monocytes." (PMID 20544025, 2010). "CCL18 and EGF are implicated in tumor biology; however, their roles in BRCA remain partly defined." (PMID 40692603, 2025). "In addition, we identified CCL18, a member of the CC chemokine family primarily secreted by monocytes, as a potential driver of tumor progression." (PMID 40552574, 2025). "Furthermore, macrophages in the Coculture group exhibited substantially elevated levels of CCL18 secretion, indicating a functional shift toward a tumor‐promoting phenotype." (PMID 40552574, 2025).